TGFBI (transforming growth factor beta induced)
Diseases named in the same sentence as TGFBI in open-access papers (continued):
Sharing a sentence is not in itself a finding about the gene and the disease.
corneal disorder (12 papers, 2007 to 2022). A non-neoplastic or neoplastic disorder that affects the cornea. "TGFBI has been associated with a range of diseases, which include nephropathy, atherosclerosis, rheumatoid arthritis, corneal disorders and malignant diseases." (PMID 34686725, 2021). "TGFBI is a downstream component of the TGF-β signaling pathway that has been implicated in corneal disorder, diabetes, and atherosclerosis as well as in the development and progression of several cancers." (PMID 28106769, 2017). "TGFBI is expressed in several organs including the skin, heart, liver, and pancreas, and has been linked to various diseases including corneal disorder, diabetes, nephropathy, wound healing, atherosclerosis, and many types of cancer." (PMID 28106769, 2017). "Mutations in the TGFBI gene are associated with an accumulation of TGFBIp in several inherited corneal disorders that lead to impaired vision." (PMID 17653042, 2007). "The present evidence against a plasma derived origin for corneal TGFBIp has implications for the pathogenesis of inherited corneal disorders caused by mutations in the TGFBI gene." (PMID 17653042, 2007). "Mutations in the transforming growth factor beta induced (TGFBI) gene encoding transforming growth factor beta induced protein (TGFBIp/keratoepithelin/βig-h3) are associated with several inherited corneal diseases with different clinical and histopathological characteristics." (PMID 23592924, 2013). "Several inherited corneal disorders in humans result from mutations in the transforming growth factor beta induced gene (TGFBI), which encodes for the extracellular transforming growth factor beta induced protein (TGFBIp) that is one of the most abundant proteins in the cornea." (PMID 17653042, 2007). "Up regulation of TGFBI has been reported in a broad variety of diseases, including corneal disorders, nephropathy, rheumatoid arthritis, cancer and atherosclerosis." (PMID 33008304, 2020). "Certain mutations in TGFBI appear to be associated with specific phenotypes of corneal disease regardless of ethnic group." (PMID 21264234, 2011). "The possibility that TGFBIp deposition in the TGFBI corneal disorders might be plasma derived was supported by the somewhat comparable human disease hypergammaglobulinemia." (PMID 17653042, 2007). "This late onset variant of LCD was thought to have an autosomal recessive mode of inheritance because it affected children of parents without corneal disease, but subsequently it became established that affected persons had a homozygous Leu527Arg mutation in TGFBI." (PMID 18385782, 2008). "In Family C, TGFBI sequence analysis in affected individuals (II.1, II.3, III.1, and IV.1) revealed two heterozygous nucleotide changes that cosegregated with the corneal disease." (PMID 21617751, 2011).
Granular corneal dystrophy (12 papers, 2009 to 2025). The presence of central, fine, whitish granular lesions in the stroma of the cornea. "This TGFBI variant is a hotspot mutation in the TGFBI gene, leading to the development of granular corneal dystrophy." (PMID 38785568, 2024). "Additionally, its indications have been expanded to include epithelial and stromal corneal dystrophies such as lattice and granular corneal dystrophy, which are associated with mutations in the transforming growth factor beta-induced (TGFBI) gene." (PMID 41464860, 2025). "Furthermore, among eight probands with the c.371G>A, p.(Arg124His) variant in TGFBI, four (4/8, 50%) had both granular corneal dystrophy and high myopia, and two (2/8, 25%) had both granular corneal dystrophy and glaucoma." (PMID 36902444, 2023). "This study investigated the TGFBI gene mutation types in outpatients clinically diagnosed with granular corneal dystrophy (GCD) prior to phototherapeutic keratectomy (PTK), also calculated the mutation rate of subjects with normal corneas, but positive family history." (PMID 28377594, 2017). "Finally, a patient with a clinical diagnosis of granular corneal dystrophy was found to be heterozygous for both R124L and ΔT125-ΔE126 mutations of TGFBI." (PMID 19461933, 2009). "The gene TGFBI (bp: 135,364,584–135,399,507) which is known to be related to granular corneal dystrophy, is exactly below D5S808 (bp: 133,533,511–133,733,691) and was sequenced first." (PMID 22194646, 2011). "Mutational analysis of the 80 patients from North India revealed typical missense mutations in exon 4 (Arg124Cys) and exon 12 (Arg555Trp) of TGFBI in most the patients with lattice corneal dystrophy (LCD) and granular corneal dystrophy (GCD), respectively." (PMID 20680100, 2010).
lattice corneal dystrophy (12 papers, 2008 to 2025). "We describe the phenotype of a variant lattice corneal dystrophy (LCD)potentially caused by a novel variant c.1772C>T p.(Ser591Phe) in exon 13of the transforming growth factor beta-induced (TGFBI)gene." (PMID 33645289, 2022). "Specific mutations in the transforming growth factor beta induced (TGFBI) gene are associated with lattice corneal dystrophy (LCD) type 1 and its variants." (PMID 23592924, 2013). "Noteworthy, the present results are in accordance with our findings from a previous study of corneal amyloid deposits caused by the V624M mutation in TGFBI, suggesting a common mechanism for lattice corneal dystrophies (LCDs) associated with mutations in the TGFBIp FAS1–4 domain." (PMID 23592924, 2013). "Given that we identified a Korean patient with lattice corneal dystrophy due to the L527R mutation in TGFBI, although this mutation is very rare, it may occur in individuals of nationalities other than Japanese." (PMID 22876129, 2012).
granular corneal dystrophy type I (11 papers, 2011 to 2025). Type I granular corneal dystrophy (GCDI) is a rare form of stromal corneal dystrophy characterized by multiple small deposits in the superficial central corneal stroma, and progressive visual impairment, which may sometimes be severe. "This was the case for a large consanguineous Tunisian family with granular corneal dystrophy type I in which homozygous members for a TGFBI mutation were the severely most affected." (PMID 34828426, 2021). "It was reported that the cleavage of the FAS1 domain occurs via proteolytic degradation by a single mutation of the FAS1 domain of the βIgH3 (TGFBI) protein with human granular corneal dystrophy type 1." (PMID 33919736, 2021).
non-small cell lung carcinoma (10 papers, 2008 to 2024). A group of at least three distinct histological types of lung cancer, including non-small cell squamous cell carcinoma, adenocarcinoma, and large cell carcinoma. "Immunohistochemistry results in non-small cell lung cancer (NSCLC) clinical samples suggested there was a strong association between elevated TGFBI expression and the response to chemotherapy." (PMID 33912443, 2021). "Blocking the binding of TGFBI to αvβ3 integrin in Non-small cell lung cancer (NSCLC) cells reduced the TGFBI pro-apoptotic actions." (PMID 38741195, 2024). "For example, miR-21-5p facilitates the multiplication of non-small cell lung cancer cells via targeting TGFBI." (PMID 34905503, 2021). "This is further supported by recent data in non-small cell lung cancer showing that TGFBI-mediated induction of apoptosis in response to chemotherapy requires the αvß3 integrin receptor." (PMID 22640878, 2012). "In addition, increased TGFBI mRNA levels correlate to a better prognosis in non-small cell lung cancer patients and a poorer prognosis in esophageal SCC patients." (PMID 39201614, 2024). "MiR-21-5p induces cell proliferation by targeting TGFBI in non-small cell lung cancer cells." (PMID 36688087, 2023).
gastric cancer (8 papers, 2010 to 2025). A primary or metastatic malignant neoplasm involving the stomach. "The GO term pathway analysis results show that ECM-associated pathways and their members, COL4A1, PXDN, and TGFBI, are involved in gastric cancer’s acquired drug resistance mechanism." (PMID 38968283, 2024). "In gastric cancer, elevated TGFBI expression significantly correlates with advanced clinical stages, high metastatic potential, and poor prognosis." (PMID 40430059, 2025). "TGFBI participates in the progression of tumors, and its expression is elevated in esophageal squamous cell carcinoma, gastric cancer, and bladder cancer." (PMID 35083181, 2022). "High TGFBI expression was associated with poor first progression (FP), OS, and PPS in gastric cancer (p < 0.001)." (PMID 34671645, 2021). "Similar to its levels in patients with gastric cancer, serum TGFBI levels were higher in biliary carcinoma as compared to non-cancer patients." (PMID 28106769, 2017). "Compared to the non-tumor controls, cholangiocarcinoma, hepatocellular carcinoma, and gastric carcinoma patients presented significantly elevated serum TGFBI levels, with cholangiocarcinoma cases having the highest values." (PMID 25889002, 2015). "We demonstrated that patients with cholangiocarcinomas, hepatic carcinomas or gastric carcinomas presented significantly elevated serum TGFBI levels, and the excess TGFBI was derived from the tumor masses." (PMID 25889002, 2015). "In summary, we revealed that patients with cholangiocarcinomas, hepatocellular carcinomas or gastric carcinomas presented elevated serum TGFBI levels." (PMID 25889002, 2015). "CCL18+TGFBI represents a good discriminator for kidney, pancreatic and stomach cancer, which are up-regulated by at least 2-fold in cancer tissues." (PMID 21060876, 2010). "Our results suggest that the suppression and/or induction of COL4A1, PXDN and TGFBI and their molecular interplays enriched in the Extracellular-related pathways may provide crucial clues to enhance the chemosensitivity of gastric cancer." (PMID 38968283, 2024). "We suggest that suppression and/or induction of COL4A1, PXDN and TGFBI and their molecular interplays enriched in the extracellular-related pathways may provide crucial clues to enhance gastric cancer’s chemosensitivity." (PMID 38968283, 2024). "Moreover, bone marrow-derived mesenchymal stem cells were shown to induce proliferation, cluster formation, and expression of the cancer stem cell marker cluster of differentiation 133 and TGFBI in co-cultured MKN7 gastric cancer cells." (PMID 28106769, 2017). "Our GO term pathway analysis results strongly suggest that suppression and/or induction of COL4A1, PXDN and TGFBI and their molecular interplays involved in the extracellular-related pathways may provide crucial clues to enhance the chemosensitivity of gastric cancer." (PMID 38968283, 2024). "TGFBI overexpression in the ECM induced the formation of gastric tumors, suggesting that TGFBI has an oncogenic function in gastric cancer." (PMID 28106769, 2017). "We suggest that suppression and/or induction of COL4A1, PXDN, and TGFBI, and their molecular interplays involved in the ECM-related pathways may provide crucial clues to enhance the chemosensitivity of gastric cancer." (PMID 38968283, 2024). "Moreover, serum TGFBI concentrations were higher in patients with cholangiocarcinoma, hepatocarcinoma, and gastric cancer than in non-tumor patients." (PMID 28106769, 2017). "Moreover, serum levels of secreted TGFBI were higher in gastric cancer as compared to non-cancerous patients." (PMID 28106769, 2017).
hepatocellular carcinoma (8 papers, 2012 to 2026). A malignant tumor that arises from hepatocytes. "Our findings here give further insights into the scavenging of fasciclin domain proteins TGFBi and POSTN, which are heavily implicated in liver fibrosis and hepatocellular carcinoma, through Stab1 and Stab2 and in liver fibrosis models." (PMID 37446152, 2023). "TGFBI interacts with integrin to promote hepatocellular carcinoma cell invasiveness, while TGFBI knockdown reduces it." (PMID 25889002, 2015). "TGFBi expression is higher in hepatocellular carcinoma, among many other tumor entities." (PMID 37446152, 2023). "Both Stabilin ligands TGFBi and POSTN are part of the extracellular matrix in normal liver tissue and have previously been described as markers in various pathological processes in the liver, including hepatocellular carcinoma." (PMID 37446152, 2023).
liver fibrosis (8 papers, 2015 to 2024). "To conclude, we show how liver fibrosis in preclinical models differentially correlates with TGFBi and POSTN levels in response to deficiency for Stab1 or Stab2, bearing consequences for potential anti-Stabilin therapies." (PMID 37446152, 2023). "Consequently, CR led to an elevation of proteomic markers associated with liver inflammation (e.g., GSTP1, GPX3) or liver fibrosis (e.g., TGFBI, TNC), and therefore, rather compromised liver health instead of improving it." (PMID 37630850, 2023). "IF staining of IMQ‐treated liver sections showed elevated TGFBi levels in male Stab1−/− mice, which were previously shown to correlate with liver fibrosis." (PMID 38946049, 2024). "In contrast, Stab‐1/2‐DKO mice present with liver fibrosis and glomerulofibrosis with increased abundance of TGFBI and POSTN, which is aggravated upon aging." (PMID 37357460, 2023). "Here, we found a very high correlation of TGFBi with liver fibrosis in all pooled experiments with pooled genotypes and treatments (R2 = 0.563, r = 0.75, p < 0.0001)." (PMID 37446152, 2023). "We also could show that there is a strong correlation between liver fibrosis and the abundance of Stabilin ligand Transforming growth factor beta‐induced (TGFBi) and Stabilin ligands are deposited in enlarged glomeruli in an age‐dependent manner." (PMID 38946049, 2024). "Stabilin ligand POSTN only correlated with the degree of liver fibrosis in WT and Stab1−/− mice across all experiments, while TGFBi, as a structurally similar ligand of both Stabilins, showed a very strong correlation with the degree of fibrosis in all genotypes in liver tissue." (PMID 37446152, 2023). "A hepatic abundance of Stabilin ligand TGFBi correlated very highly with liver fibrosis levels." (PMID 37446152, 2023). "Lumican and TGFBI have previously been reported as tissue markers of liver fibrosis." (PMID 25909381, 2015). "Stabilin‐1 and Stabilin‐2 scavenge their ligands POSTN and TGFBI from the circulation, no liver fibrosis and glomerulofibrosis is obvious in wildtype mice aged for 12 months." (PMID 37357460, 2023).
mesothelioma (8 papers, 2012 to 2024). A usually malignant and aggressive neoplasm of the mesothelium which is often associated with exposure to asbestos. "Previous studies have reported that TGFBI play as irreplaceable role in inducing suppressive mesothelioma tumorigenesis and progression through the PI3K/Akt signaling pathway." (PMID 34671645, 2021). "Our data show that the telomerase activity of TGFBI-expressing mesothelioma cells is significantly higher than that of controls (P < 0.01)." (PMID 22695319, 2012). "Although the number of TGFBI-expressing mesothelioma cells in the S phase increased over time, it remained significantly lower than that of the control cells at all evaluated points in time, specifically 4, 8, 24, and 32 h after serum stimulation." (PMID 22695319, 2012). "Moreover, it has also been described that TGFBI is involved in mesothelioma progression through the AKT/mTOR pathway which could be related to the HER2 pathway changes observed in TGFBI overexpression and mutagenesis." (PMID 31277676, 2019). "Additionally, except CESC, CHOL, mesothelioma (MESO), READ, SARC, UCEC and UCS, TGFBI expression was significantly correlated with immunostimulatory genes." (PMID 34671645, 2021). "This indicated that TGFBI could not recovery expression of p16 and p14 in mesothelioma cells with biallelic deletion." (PMID 22695319, 2012).
esophageal squamous cell carcinoma (7 papers, 2014 to 2025). Esophageal squamous cell carcinoma (ESCC) is a type of esophageal carcinoma (EC) that can affect any part of the esophagus, but is usually located in the upper or middle third. "In esophageal squamous cell carcinoma (ESCC), elevated TGFBI expression correlates with a higher risk of hematogenous relapse and adverse patient outcomes, indicating its potential as a therapeutic target." (PMID 40510341, 2025). "Again, MMP-13 and TGFBI expression is elevated in esophageal squamous cell carcinoma." (PMID 25369402, 2014). "TGFBI expression was found to be upregulated in esophageal squamous cell carcinoma (ESCC) as compared to non-cancerous tissues, by microarray and reverse transcription PCR analyses." (PMID 28106769, 2017).
head and neck squamous cell carcinoma (7 papers, 2019 to 2025). A squamous cell carcinoma that arises from any of the following anatomic sites: lip and oral cavity, nasal cavity, paranasal sinuses, pharynx, larynx, and salivary glands. "For example, CPSF1 promotes head and neck squamous cell carcinoma growth by regulating AS in cancer-associated genes, such as AKT2, HRAS, TGFBI, and UBE2C." (PMID 33748106, 2021). "In head and neck squamous cell carcinoma (HNSCC), TGFBI significantly influences cancer stem cell traits and epithelial-mesenchymal transition (EMT), highlighting its role in tumor aggressiveness and metastasis potential." (PMID 40510341, 2025). "We previously showed that p-EMT genes such as SERPINE1, ITGA5, TGFBI, P4HA2, CDH13, and LAMC2 are potent poor prognostic markers in head and neck squamous cell carcinoma (HNSCC) patients by bioinformatic analysis." (PMID 34294795, 2021).
osteosarcoma (7 papers, 2012 to 2024). A usually aggressive malignant bone-forming mesenchymal neoplasm, predominantly affecting adolescents and young adults. "In the present study, we revealed that niclosamide can effectively inhibit the cell migration and invasion of osteosarcoma cell lines by reducing the expression of TGFBI." (PMID 35008910, 2022). "A previous study demonstrated that TGFBI knockdown effectively inhibited the cell invasion and migration of osteosarcoma." (PMID 35008910, 2022). "Similarly, our results demonstrated that niclosamide inhibited the migration and invasion of human osteosarcoma cells via repressing the TGFBI expression." (PMID 35008910, 2022). "Although niclosamide has been considered to be a potential anticancer drug, the molecular mechanism underlying its inhibition of TGFBI expression and osteosarcoma metastasis has not been well delineated." (PMID 35008910, 2022). "Therefore, TGFBI derived from osteosarcoma cells via the ERK pathway contributed to cellular migration and invasion and niclosamide inhibited these processes." (PMID 35008910, 2022). "In conclusion, our study is first to demonstrate that niclosamide suppresses the migration and invasion of human osteosarcoma U2OS and HOS cells by inhibiting TGFBI expression via the ERK signaling pathway." (PMID 35008910, 2022). "Mechanistically, TGFBI propels cancer progression by activating αvβ5 integrin signaling, ultimately engaging Src, FAK, PI3K, and AKT through its RGD motif, as observed in models of osteosarcoma, colon, and pancreatic cancer." (PMID 38514830, 2024). "The results indicated that niclosamide, at concentrations of up to 200 nM, inhibited the migration and invasion of human osteosarcoma U2OS and HOS cells and repressed the transforming growth factor beta-induced protein (TGFBI) expression of U2OS cells, without cytotoxicity." (PMID 35008910, 2022).